MIR29B2 (microRNA 29b-2)
Synonyms: hsa-mir-29b-2; MIRN29B2
Gene: MicroRNA gene on chromosome 1 (207,802,443 to 207,802,523, reverse strand). Ensembl gene ENSG00000284203.
Gene Ontology:
Biological process: miRNA-mediated post-transcriptional gene silencing
Cellular component: RISC complex
Homologues: Orthologues: chimpanzee ptr-mir-29b-2 (100% identical), macaque mml-mir-29b-2 (100% identical), mouse Mir29b-2 (100% identical), pig ssc-mir-29b-2 (100% identical), rabbit MIR29B2 (100% identical), rat Mir29b-3 (100% identical), guinea pig MIR29B2 (99% identical), tropical clawed frog xtr-mir-29b (85% identical), zebrafish dre-mir-29b-1 (74% identical). Paralogues in human: MIR29B1 (80% identical), MIR29C (60% identical), MIR29A (53% identical).